BRCA1 (BRCA1 DNA repair associated)
Diseases named in the same sentence as BRCA1 in open-access papers (continued):
Sharing a sentence is not in itself a finding about the gene and the disease.
tumor (continued). "Interestingly, both tumour subtypes GATA3–METH and GATA3–LOFDEL are significantly enriched in the molecular signature of mutated BRCA1." (PMID 40585280, 2025). "Given the complexity of HRD biomarkers, key assay features include the selection of HRR genes (BRCA1, BRCA2, PALB2, RAD51C, RAD51D), definitions of genomic scars (LOH, TAI, LST), mutational signatures analyzed, use of comparator samples, and tumor-specific HRD score calculations." (PMID 40864792, 2025). "Although BRCA1/2-associated HGSOCs almost always carry a somatic deletion of the remaining allele of the gene (loss-of-heterozygosity, LOH) detected in the gross tumor mass, some tumors have a small admixture of platinum-resistant cells with a preserved WT copy of the involved BRCA gene." (PMID 40547808, 2025). "Therefore, the oncological safety of SSM/NSM should be re-evaluated for non-BRCA1/2 PV carriers regarding superficial margins, residual tumor foci within the skin flap, and residual breast tissue." (PMID 40042736, 2025). "Despite accumulated neoantigen production in the BRCA1-MT group, the heterogeneous expression of HLA-related genes within tumor cells may impair immune cell recruitment and ICI response in this group." (PMID 40904511, 2025). "Molecular findings, including BRCA1/2 mutations, homologous recombination deficiency (HRD) status, loss of heterozygosity (LOH) scores, and HRR-related gene alterations, were correlated with tumor board recommendations and decisions for PARPi therapy." (PMID 41323499, 2025). "The presence of either BRCA1/2 alteration or a GIS > 42 defines a tumor as HRD positive." (PMID 41465396, 2025). "The BRCA1 protein accounts for its ability to maintain genomic integrity and suppress tumor formation through several cellular processes, such as the DNA damage repair pathway, transcription regulation, cell cycle progression, apoptosis, and protein ubiquitination." (PMID 41155174, 2025). "In the JAVELIN tumour-agnostic study, which evaluated the combination of anti-PD-L1 avelumab and PARPi talazoparib in patients with BRCA1/2 or ATM pathogenic alterations, ORR was 26.4%, thereby not meeting the prespecified target ORR of 40%." (PMID 41188872, 2025). "Moreover, after DNA damage, cells expressing Klf4 exhibited increased levels of BRCA1 and Rad51, known tumor suppressor genes." (PMID 40699616, 2025). "BRCA1 mimetics have the potential to overcome resistance to hormonal therapies by directly modulating the estrogen receptor, reducing estrogen signaling, and enhancing tumor suppression pathways." (PMID 40283136, 2025). "In a tumor-agnostic cohort study by Zhou and colleagues, those with BRCA1 or BRCA2 alterations had higher median TMB than their wild-type counterparts (24.6 vs. 5.9, p < 0.001) and comprised a higher proportion with high-TMB tumors (defined as the top 10% of TMB in each tumor type)." (PMID 40426860, 2025). "BRCA1 is part of an obligate multifunctional heterodimer with BRCA1-associated RING domain 1 (BARD1), acting together as a tumor-suppressor E3 ubiquitin ligase involved in repairing double-strand DNA breaks through homologous recombination, maintaining genome stability." (PMID 39860065, 2025). "Tumours with high P-cadherin expression were significantly associated with worse overall survival, especially in the subgroup without BRCA1/2 mutations." (PMID 40320493, 2025). "Its capacity to resolve exon-level CNVs in highly heterogeneous samples makes it particularly suitable for APC and other malignancies characterized by high intratumoral heterogeneity, where only a small fraction of tumor cells may harbor BRCA1/2 alterations." (PMID 40725150, 2025). "In addition, BBIT20-treated tumours showed a reduced number of BRCA1- and RAD51- positive cells, supporting the inhibitory effect of BBIT20 on HR." (PMID 40275348, 2025). "Like BRCA1/2, germline PALB2 mutations cause HRD and genomic instability in tumors, which enable DNA damage and may affect the aggressiveness of the tumor." (PMID 41374970, 2025).
tumor (continued). "Obesity, for example, exacerbates the oncogenic potential of BRCA1 and BRCA2 mutations by increasing systemic inflammation, hormonal imbalances, and estrogen levels derived from adipose tissue, creating an environment that promotes tumor development." (PMID 40277318, 2025). "Despite BRCA1 status are not significantly correlated with immune cell content, BRCA1 mutation-mediated TME still exhibits more anti-tumor activity." (PMID 40904511, 2025). "This assay is not limited to BRCA1 synthetic lethal relationships and could potentially be applied to any cell or tumour type that has a genetic vulnerability that leads to a selective pharmaceutical sensitivity in 2D or 3D." (PMID 40982437, 2025). "We have also demonstrated earlier that Brca1 mutant tumor are largely ERα positive at the initiation stages and gradually become ERα negative during their progression, however the molecular changes responsible for the conversation from ERα positive to negative remains elusive." (PMID 41318657, 2025). "Similarly, preclinical studies in Brca1/2-deficient breast cancer mouse models showed that olaparib, a selective PARP inhibitor, enhanced the anti-tumor efficacy of platinum-based therapies, leading to profound tumor growth suppression." (PMID 40563367, 2025). "However, using archival tumor samples, the OCTOVA trial plans further biomarker analyses to assess tumor HRD status, including BRCA1/2 mutation status." (PMID 40427127, 2025). "This is in line with other studies showing an association between tumor mutation burden, but not BRCA1/2 mutations, and TLS formation." (PMID 39751944, 2025). "BRCA1 participated in tumor immune suppression and T lymphocyte infiltration of HCC." (PMID 40404896, 2025). "PDX474.7, one of the selected models, was the most resistant of the whole cohort and displayed a BRCA2 mutation, whereas the other one, PDX252, was a BRCA1 mutant, where olaparib slows down tumor growth without achieving disease control." (PMID 41273720, 2025). "PARP inhibitors are also approved in the treatment of BRCA2-deficient tumours: however, mechanisms of PARPi resistance differ substantially compared to cells lacking BRCA1." (PMID 39994444, 2025). "Furthermore, differences in tumor biology and systemic therapy response between BRCA1 and BRCA2 carriers require individualized strategies." (PMID 41302125, 2025). "Different types of biomarkers used for the prognosis of BC comprise BRCA1/2 gene mutations, serum biomarkers like carcinoembryonic antigen (CEA) or cancer antigen 15-3 (CA 15-3), circulating tumor-derived DNA, circulating tumor cells, and a multi-analyte profile of Oncotype DX or uPA/PAI-1, etc.." (PMID 41050086, 2025). "Additionally, a high level of PD-L1 expression is detected in the tumor stroma in BRCA1-mutated TNBC, indicating the existence of immune exhaustion in the HRD tumor stroma." (PMID 40830526, 2025). "Studies reveal that tumor cells with BRCA1/2 deficiencies exhibit high sensitivity to PARP inhibitors, a phenomenon termed “synthetic lethality,” meaning that inhibiting PARP in a BRCA-deficient background results in tumor cell death." (PMID 40370464, 2025). "This could also indicate that more molecules can influence BRCA1 function in the tumor microenvironment, and CD44 as main HA receptor could be the link between HA metabolism and the DNA repair process in tumors." (PMID 41373491, 2025).
tumor (continued). "Olaparib is the standard of care for advanced metastatic PDAC with BRCA1/2 mutations, but it is not yet approved for BRCA1/2‐like neoplasms." (PMID 41473825, 2025). "The example of Brca1 therefore suggests that EMT, which is classically associated with the metastatic cascade, can also be a major feature of tumor cell heterogeneity by overcoming luminal lineage restriction and shaping tumor identity." (PMID 40676433, 2025). "BRCA1 is a tumor-suppressor gene involved in DNA repair and cell-cycle control." (PMID 41301948, 2025). "In both university hospitals (the testing centers) included in the current study, gene panels for the tumor test expanded over time from analysis of BRCA1/2 only to also testing for BRIP1, RAD51C, RAD51D and PALB2, which is in line with the latest national guideline." (PMID 40323485, 2025). "According to this model, if a BRCA1 germline mutation is present, the “healthy” allele must first be compromised in the sense of LOH resulting in increased DNA double-strand breaks by homologous recombination deficiency (HRD) in order for a tumor to develop." (PMID 40519304, 2025). "Additionally, tumor tissue undergoes reflex NGS testing for BRCA1/2 to assess eligibility for PARPi." (PMID 41046341, 2025). "BRCA1/2 functional loss leads to impaired HRR pathways, thereby preventing cells from effectively repairing platinum‐induced DNA damage, resulting in cell cycle arrest, and ultimately enhancing tumor cell sensitivity to platinum‐based chemotherapy." (PMID 41473689, 2025). "Importantly, BRCA1 was also detected at the invasive front and in the detached tumor cells, suggesting its possible involvement in epithelial-mesenchymal transition (EMT) processes via regulation of E-cadherin and vimentin levels." (PMID 40224184, 2025). "This could become even more important if guidelines are modified to include additional tumor types for which PARP inhibitors could be effective based on BRCA1 and BRCA2 status." (PMID 40853717, 2025). "BRCA1–/– tumor showed a decrease in tumor volume and weight in response to Olaparib, as expected." (PMID 41243969, 2025). "This study in a cohort of 237 patients encompassing 24 different tumor entities assessed by a molecular tumor board shows that inactivating alterations of BRCA1/2 are not always associated with an elevated genomic instability score." (PMID 40278800, 2025). "Consistently, there was no subgroup difference for rearrangement signatures characteristic of BRCA1- or BRCA27 nor for tumor mutational burden (two-sided Kruskal-Wallis test, p > 0.05)." (PMID 40155623, 2025). "Notably, the BRCA1 CNV profiles of the organoids closely matched those of their corresponding tumor tissues with 100% concordance, confirming that the PDOs faithfully preserved the genomic alteration patterns of their parental tumors." (PMID 41463218, 2025). "We found that BRCA1 was highly expressed in various tumor types, including BRCA." (PMID 38224491, 2024). "BRCA1/2 gene revers mutation can recover the Open Reading Frame (ORF) of BRCA1/2 to restore protein expression, and eventually lead to PARPi resistance in tumor cells through accumulation of cytogenetic mechanisms." (PMID 39318358, 2024). "There was no reversion of the BRCA1 mutation in somatic tumor tissue of both patients throughout their clinical course." (PMID 38315150, 2024).
tumor (continued). "Furthermore, nationally implemented quality control standards ensure the high-quality implementation of reliable BRCA1/2 tumor testing." (PMID 38730634, 2024). "Higher PD-1 expression on CD8+ T cells in BRCA1/2 mutant tumours may be beneficial in enhancing the effects of immune checkpoint inhibitors." (PMID 39530091, 2024). "As BRCA1/BRCA2 proteins are responsible for the repair of double-strand DNA breaks (DSBs), the presence of pathogenic variants in BRCA2 leads to the impaired activity of its protein product and thus increases the risk of a DSB in a tumor cell." (PMID 39456660, 2024). "Here, we hypothesize that the necessary genetic modifications for oncogenesis in the context of BRCA1/BRCA2 inactivation may arise from recurrent copy number alterations (CNAs) present in these neoplasms." (PMID 39198848, 2024). "BRCA1 and/or BRCA2 gene mutations have since been shown to play a role in many more tumor types." (PMID 38540206, 2024). "The role of the BRCA1 (BReast-CAncer susceptibility gene 1) protein in regulating the 6-TG-induced MMR damage response: BRCA1 is a tumor suppressor gene involved in a variety of key cellular processes contributing to DNA repair and transcriptional regulation in response to DNA damage." (PMID 39186800, 2024). "The BRCA1 gene acts as a tumor suppressor through its role in DNA repair." (PMID 38063999, 2024). "We observed significantly younger age of onset and higher tumor nuclear grade for BRCA1/2 mutation carriers compared to non-carriers." (PMID 38689097, 2024). "Thus, the lack of PD-L1 can lead to increased DNA damage accumulation and improved tumor control of PARP inhibition in BRCA1 wild-type tumors, while triggering synthetic lethality to PARP inhibitors in vitro." (PMID 39156700, 2024). "Results on the prognostic value of tumor BRCA1-PM in TNBC patients have been conflicting, which may be due to different methods to analyze BRCA1-PM status, different reference groups (including gBRCA1m patients or not), or different treatments." (PMID 38191387, 2024). "They found that the BRCA1mut-FTE organoids exhibited a series of cell abnormalities consistent with tumor transformation compared to the control FTE organoids without BRCA1 mutation." (PMID 38509422, 2024). "Another hypothesis suggests that NO may play a role in sensitising BRCA1/2-proficient tumours to PARPi by inhibiting homologous recombination repair (HRR) pathways." (PMID 39768338, 2024). "We then performed cologenic assays to further evaluate the sensitivity of the cells to PARPi and found that OLA slightly reduced the colony formation of Brca1+/+;Gata3+/+ tumor cells but significantly inhibited the colony formation of Brca1+/− or Gata3+/− tumor cells." (PMID 38627785, 2024). "Given that inheritance of a BRCA1 or BRCA2 mutation correlates with earlier onset of disease, aggressive tumor behavior, and heightened recurrence risk, targeted therapies such as oral poly(ADP-ribose) polymerase (PARP) inhibitors offer potential additional treatments for these patients." (PMID 38826792, 2024). "The breast cancer tumor-suppressor proteins BRCA1 and BRCA2 are important for DSB repair by homologous recombination (HR), and their dysfunction (deficiency) was shown to sensitize cells to PARP inhibition, resulting in chromosomal instability, cell cycle arrest, and subsequent apoptosis." (PMID 39684238, 2024).
tumor (continued). "Thus, BRCA1/2 mutations, along with mutations in other mutator genes like ATM and CHEK2, have been exploited as tumor-agnostic markers, but in a unique application." (PMID 38920700, 2024). "In this work, the analysis of tumor sequences showed loss of the germline reference allele (LOH) in all patients carrying germline variants classified as pathogenic or likely pathogenic, except for one carrier of the variant BRCA1:c.4964C>T (p.Ser1655Phe)." (PMID 38308422, 2024). "Interestingly, despite reduced angiogenesis, VEGFR2 inhibition in combination with talazoparib only modestly reduced tumor growth in the Brca1-def and Bard1-def models (EV2D), suggesting that other mechanisms are important for driving in-vivo PARPi resistance." (PMID 38956205, 2024). "Studies have demonstrated that antiangiogenic drugs have multiple effects on homologous recombination deficiency (HRD), including reducing angiogenesis, creating hypoxia in tumor microenvironment, and downregulating BRCA1/2 and RAD51, two of the most important components in HRD." (PMID 39624625, 2024). "In addition, VEGFR2 inhibition in combination with talazoparib only modestly reduced tumor growth in the Brca1-def and Bard1-def models, whereas Flt1 inhibition in combination with talazoparib resulted in prominent tumor regression." (PMID 38956205, 2024). "Tumor tests were performed for 502 patients (50.2%) and BRCA1/2 TPVs were detected in 14.7%." (PMID 38730634, 2024). "Furthermore, gBRCA1m was associated with higher (adjusted subdistribution HR, 4.04; 95% CI, 2.29–7.13) and tumor BRCA1-PM with lower (adjusted subdistribution HR, 0.42; 95% CI, 0.19–0.95) incidence of second primary tumors, compared to BRCA1-non-alteration." (PMID 38191387, 2024). "In addition, it has been shown that there is a concordance between BRCA1 epimutations in WBCs and tumor tissues." (PMID 38542081, 2024). "Despite a lack of evidence of quality differences, we emphasize that adequate reporting and internal and external quality monitors are essential for the high-quality implementation and execution of reliable BRCA1/2 tumor testing, which is crucial for identifying all patients with BRCA1/2 TPVs." (PMID 38730634, 2024). "The first BOADICEA prediction model integrated the risk due to the rare loss-of-function variants in the “major genes” (BRCA1 and 2, PALB2, CHEK2 and ATM) with tumor pathology (receptors status), basic demographic element (e.g., year and country of birth and family ethnicity), and family history." (PMID 38397209, 2024). "In particular, we observed reduced numbers of CD8+ T cells in PARPi-resistant, but not PARPi-sensitive, tumors from the Brca1- and Bard1-deficient tumor models." (PMID 38956205, 2024). "Furthermore, he has studied histone deacetylase 8 (HDAC8), BRCA1, YWHAE-FAME22 rearrangement, Cyclin D1, tumor cell necrosis (TCN), and BCRO as diagnostic markers for uLMS." (PMID 38410101, 2024). "The remaining patient exhibited a germline BRCA1 rearrangement but lacked a tumor BRCA (tBRCA) mutation." (PMID 38869771, 2024). "AKT inhibitor treatment of tumor-bearing BRCA1-mutant mice significantly reduced tumor volume." (PMID 38977680, 2024). "Interestingly, the BARD1 protein interacts with BRCA1 (BRCA1-BARD1) forming a tumor suppressor complex, which is an E3 ubiquitin ligase necessary for DNA double-strand breaks repair by RAD51-mediated homologous recombination." (PMID 38978731, 2024).